IL13 (interleukin 13)
Diseases named in the same sentence as IL13 in open-access papers (continued):
Sharing a sentence is not in itself a finding about the gene and the disease.
periodontal disease (8 papers, 2016 to 2025). "The aim of this study was to use a meta-analysis to evaluate the relationship between the IL-13-1112C/T polymorphism and susceptibility to periodontal disease." (PMID 29415708, 2018). "Interleukin-4 (IL-4) and interleukin-13 (IL-13) are anti-inflammatory cytokines and several polymorphisms of them have been proved involved in periodontal disease." (PMID 27195298, 2016). "Similarly, Allium sativum (garlic) extract was shown to elevate IL-10 and IL-13 levels, providing protective effects against alveolar bone loss and promoting anti-inflammatory responses in periodontal disease." (PMID 39539670, 2024). "In periodontal diseases, IL-10 and IL-13 are involved in modulating the immune response and in the suppression of pro-inflammatory cytokines by monocytes/macrophages, respectively." (PMID 31973090, 2020). "Furthermore, other downstream cytokines, including IL-2, IL-8, TNF-α, and IL-13, were also statistically significantly (p < 0.05) increased as periodontal disease severity increased, supporting a heightened inflammatory response." (PMID 41303313, 2025).
psoriatic arthritis (8 papers, 2012 to 2023). Joint inflammation associated with psoriasis. "The mechanism surrounding IL-4/IL-13 blocking-induced enthesitis are presently unknown, but genetic associations of unknown functional significance between IL-13 and psoriatic arthritis have been reported." (PMID 33544244, 2021). "Similarly, IL-13 is also identified as a risk locus for psoriatic arthritis investigated in a number of studies." (PMID 28642550, 2017). "On the other hand, polymorphisms in IL23R, TNFAIP3, PTPN22 (tyrosine-protein phosphatase non-receptor type 22), IL12B, RUNX1 (CD8-lymphocyte activation and differentiation), IL13, KIR (killer-cell immunoglobulin-like receptor), and MAGI1 genes have shown association with psoriatic arthritis." (PMID 37628670, 2023). "Subsequent studies confirmed this result, but also showed that mRNA encoding the α1 chain of the IL-13 receptor is over-expressed in lesional skin relative to normal skin from healthy controls, and further demonstrated that IL-13 is elevated in synovial fluid of patients with psoriatic arthritis." (PMID 22479649, 2012).
pulmonary TB (8 papers, 2012 to 2025). "Importantly, IL13 rs20541 polymorphism has been linked with susceptibility to pulmonary tuberculosis, Schistosoma mansoni infection, hand, foot, and mouth diseases, further strengthening its possibility of the beneficial selection of genetic variants in the studied population." (PMID 39088580, 2024). "We demonstrated that host C1q plasma levels and IL-13-specific response to rmsHBHA differentiate active form of pulmonary TB from cured disease." (PMID 38545118, 2024). "This study provides new information on host immune responses throughout the course of anti-TB treatment, and enables the identification of a plasma protein signature, composed of C1q and IL-13-specific response to rmsHBHA, capable of differentiating an active form of pulmonary TB from cured disease." (PMID 38545118, 2024). "To validate our results in human TB patients, we here determined the association of distinct variants of the IL4, IL13, IL4RA, IL13RA1, and IL13RA2 genes with cavity formation in a large Ghanaian cohort of HIV-negative individuals with newly diagnosed pulmonary TB." (PMID 26977119, 2016). "For identification of adult pulmonary TB, regardless of HIV status, we identified an 8-marker signature consisting of FGF, IL-1β, IL-8, IL-10, IL-12p70, IL-13, MIP-1β and VEGF which gave an AUC of 0.78 (95% CI: 0.75, 0.84), sensitivity of 79% (95% CI: 75, 84) and specificity of 67% (95% CI: 60, 73)." (PMID 41164199, 2025).
schizophrenia (8 papers, 2014 to 2025). A major psychotic disorder characterized by abnormalities in the perception or expression of reality. "The cytokines produced by Th2 (IL-4, IL-5, and IL-13) were also increased in patients with schizophrenia (P < 0.001; P < 0.001; P = 0.012, respectively)." (PMID 35223927, 2022). "From these results, it is highly probable that anti-inflammatory responses mediated by IL-10 and IL-13, which reflect M2 polarization of microglia, occur in the CNS of schizophrenia patients." (PMID 25429645, 2014). "Recently, relatively higher amounts of IL-10 and IL-13 have been found in the CSF and blood from patients with schizophrenia." (PMID 25429645, 2014). "Furthermore, a positive correlation between the total PANSS score and increased concentrations of IL-1β, sIL-2R, IL-13, IL-6, and IL-17 in chronic patients with schizophrenia was found." (PMID 40364201, 2025). "In schizophrenia, neuroinflammation denotes the initiation of the brain’s immune response, which is principally driven by microglial cells and the discharge of inflammatory cytokines like IL-2, IL-4, IL-13 IFN-γ, and TNF-α." (PMID 38256307, 2023). "The fewest relations were observed between cytokine levels and negative symptoms of schizophrenia: only IL-1, IL-6, IL-13, and TNF-β were positively correlated with the negative-symptom PANSS score." (PMID 36556337, 2022). "Elevations of IL-1β, IL-6, IL-8, IL-4, and TNF-α may also exacerbate negative symptoms of schizophrenia, whereas IL-6, together with IL-13 and IL-17, may intensify general symptoms in chronic schizophrenia." (PMID 40364201, 2025). "For testing of cohort 9, which comprised help-seeking prodromal individuals (18 who later developed schizophrenia and 58 who did not), the assays for CA, IL10, IL13 and SGOT were excluded for failing QC, resulting in a 22-analyte panel (the same panel tested on cohort 6)." (PMID 26171982, 2015).
urticaria (8 papers, 2010 to 2025). A vascular reaction of the skin characterized by erythema and wheal formation due to localized increase of vascular permeability. "The association of IL-13 with TNF α was seen only in urticaria patients." (PMID 20616938, 2010). "Despite the limited sample size in the different clinical phenotypes, our results confirm these previous data indicating that, in the presence of Pru p 3, ILC2 can produce higher levels of IL-13 in anaphylactic LTP-AP than in urticaria." (PMID 38725998, 2024). "Studies regarding IL-31 and urticaria were mainly concerning disease severity and therapy exploitations, as basophils have been found to produce pro-inflammatory cytokines (IL-4 and IL-13), after the interaction of IL-31/IL-31R." (PMID 35742951, 2022). "In addition, the level of IL-13 was lower among the ST treatment group (at 10 μg/mL), whereby IL-13 is thought to be a marker of urticaria severity." (PMID 29849717, 2018).
autism (7 papers, 2011 to 2025). Persistent deficits in social interaction and communication and interaction as well as a markedly restricted repertoire of activity and interest as well as repetitive patterns of behavior. "Among the drugs connected to the remaining PND-related genes, we highlight those that act upon IL13 for autism and CEACAM5 for bipolar disorder." (PMID 32398742, 2020). "In addition, reports consistently delineate unchanged IL-13, IL-10, IL-5, and IL-4 levels in the plasma/serum and post-stimulated blood immune cells in individuals with autism as compared with controls." (PMID 36268027, 2022). "Three other drugs were also found to target IL13, which could be used to reduce the inflammatory response in autism." (PMID 32398742, 2020). "In certain subtypes of the autism spectrum there is evidence for increases in blood levels of IL4 and/or IL13." (PMID 29232822, 2017). "Here, IL13 was found to be targeted by drugs that have never been tested for autism." (PMID 32398742, 2020). "The Th1-Th2 paradigm, that is immune skewing toward type-1 cell-mediated immunity (interferon-gamma promoted immunity) vs. type-2 humoral immunity (IL-4, IL-5 and IL-13 promoted immunity), may not be properly applicable to immune alterations in autism." (PMID 21799730, 2011). "Therefore, our findings indicate that increased production of Th1 cytokines (IFN-γ) and Th17 cytokines (IL-17), along with no change in Th2 cytokines (IL-4, IL-5, and IL-13), might suggest a skewing toward the Th1/Th17 phenotype and dampening of the Th2 phenotype in the context of autism." (PMID 36268027, 2022).
bronchiectasis (7 papers, 2014 to 2025). Segmental, irreversible dilation of the bronchial tree resulting in the accumulation of secretions which leads to obstruction. "In these studies involving smaller cohorts, King and colleagues demonstrated that persistent or recurrent lower respiratory infection with NTHi in adults with COPD (n = 39) or bronchiectasis (n = 16) was associated with high IL-13 production in the airways and low systemic IFN-γ production." (PMID 25111142, 2014). "Expression of IL-8 and IL-13 was significantly lower in this phenotype compared to the others, as well as the levels of FeNO, a biomarker usually associated with high eosinophil count in asthma, and observed in patients with steady bronchiectasis in comparison with healthy individuals." (PMID 41149860, 2025). "In bronchiectasis, increased sputum eosinophils are related to greater bronchodilator reversibility and higher levels of FeNO, IL-13 and an increase in sputum Eosinophil Peroxidase (EPX)." (PMID 41149860, 2025).
bullous pemphigoid (7 papers, 2018 to 2026). Bullous pemphigoid (BP) is the most common form of autoimmune bullous dermatosis. "Dupilumab, a monoclonal antibody blocking the receptor binding of interleukin-4 (IL-4) and interleukin-13 (IL-13), has been successfully used to treat spontaneous forms of bullous pemphigoid (BP)." (PMID 40507326, 2025). "Its efficacy has extended to other Th2-driven dermatoses including prurigo nodularis and bullous pemphigoid, highlighting the central role of IL-4/IL-13 in these diseases." (PMID 41226755, 2025). "We found that, similar to the spontaneous form of bullous pemphigoid (BP), interleukin-4 (IL-4) and interleukin-13 (IL-13) were upregulated." (PMID 40507326, 2025). "- Bullous pemphigoid displays a clear Th2-mediated inflammatory response, characterized by IL-4, IL-5, and IL-13, eosinophil recruitment and pruritus." (PMID 41479908, 2025). "Our review identified keratinocytes as crucial mediators in bullous pemphigoid, predominantly orchestrating Th2-driven inflammation through secretion of cytokines including IL-16, leading to CD4+ T cells recruitment and amplification of the IL-4/IL-13 axis." (PMID 41479908, 2025).
cervical cancer (7 papers, 2013 to 2024). A primary or metastatic malignant neoplasm involving the cervix. "Tumor-derived thymic stromal lymphopoietin (TSLP) can activate eosinophil to increase the expression of IL-4, IL-5, IL-10 and IL-13, and promote the proliferation of cervical cancer cells." (PMID 36874093, 2023). "In patients affected by HPV-related cervical cancer, apoptotic cells originated by the epithelium turnover are phagocytosed by dendritic cells that release immunosuppressive cytokines as TGFb, IL10, and IL13." (PMID 24455729, 2013).
chronic rhinosinusitis with nasal polyps (7 papers, 2022 to 2026). A type of chronic rhinosinusitis that is characterized by the presence of nasal polyps. "Chronic rhinosinusitis with nasal polyps (CRSwNP) and eosinophilic otitis media (EOM) are both manifestations of type 2 (Th2-mediated) inflammation, characterized by elevated levels of interleukin (IL)-4, IL-5, and IL-13, leading to eosinophilic infiltration of mucosal tissues." (PMID 40870516, 2025).
Erythema (7 papers, 2020 to 2026). Redness of the skin, caused by hyperemia of the capillaries in the lower layers of the skin. "Clinical symptoms, including erythema, edema, and crusting, were monitored, and serum levels of IL-4, IL-13, IgE, and histamine were quantified using ELISA." (PMID 41646846, 2026). "In AD or PN with prominent erythema and barrier dysfunction—where IL-4 and IL-13 are likely elevated—nemolizumab may transiently increase TARC and activate Th2 responses, raising the risk of Th2-related AEs." (PMID 40364058, 2025). "Kif3aK14∆/∆ mice skin appeared normal without lesions or erythema by H&E staining and no baseline inflammation was observed in the skin by IL-4 and IL-13 qPCR, and CD3 staining." (PMID 32796837, 2020).
hookworm infection (7 papers, 2011 to 2023). "IL-13, in particular, is increased in the presence of hookworm infection and a dominant mediator of fibrotic tissue, which induces fibrosis independently and via simulation and activation of transforming growth factor (TGF)-β." (PMID 28542260, 2017). "Our results show that experimental hookworm infection leads to a strong systemic and mucosal Th2 (IL-4, IL-5, IL-9 and IL-13) and regulatory (IL-10 and TGF-β) response, with some evidence of a Th1 (IFN-γ and IL-2) response." (PMID 22346753, 2012). "Levels of mRNA encoded by the Th2/Th9 genes IL-4, IL-5, IL-13, IL-9 and GATA-3 appeared unaffected by hookworm infection using this technique." (PMID 22346753, 2012). "IL-33 protects against experimental cerebral malaria by driving the expansion of ILC2s and their production of IL-4, IL-5 and IL-13 and is required for ILC2-derived IL-13- but not IL-4-driven Type 2 responses during hookworm infection." (PMID 28168040, 2017). "A significant increase in IL-5 produced in response to QE65 was seen after hookworm infection (week 20), with a non-significant trend for increased production of IL-13." (PMID 21949691, 2011).
hyperreactivity (7 papers, 2010 to 2024). "In this study, treatment with anti‐S100A4 antibody significantly inhibited Th2-mediated airway hyperreactivity and reduced the production of IL-4 and IL-13." (PMID 37873538, 2023). "We measured BAL CCL11 (eotaxin, an eosinophil chemoattractant), IL-23p19, IL-6, CXCL2 (pro-neutrophilic mediators), CCL20 (a lymphocyte chemoattractant), and IL-13 (known to prime smooth muscle cells for airway hyperreactivity)." (PMID 31572383, 2019). "A recent report suggested that pulmonary IL-13 is responsible for the viral induced lung inflammation and airway hyperreactivity." (PMID 23555047, 2013).
injury (7 papers, 2016 to 2025). Damage inflicted on the body as the direct or indirect result of an external force, with or without disruption of structural continuity. "While IL-13 has been demonstrated to be neuroprotective by modulating microglia/macrophage responses in traumatic brain injury, other studies have shown that IL-13 can be detrimental to neuronal survival." (PMID 34654436, 2021). "A previous study has demonstrated that IL-13 is a mediator, and possibly a therapeutic target, in radiation-induced lung injury, as shown by saturating fraction of the circulating decoy receptor IL-13Rα2." (PMID 33569004, 2020). "To assess the broader relevance of these findings, we investigated the contribution of pulmonary IL-13 to host defense against Staphylococcus aureus as well as upon induction of lipopolysaccharide (LPS)-induced acute lung injury." (PMID 28228256, 2017). "We next sought to determine if the function of IL-13 is additive to, or independent from, another pro-fibrotic cytokine implicated in radiation lung injury, TGF-β, by examining the expression of TGF-β and fibrosis-associated genes driven by TGF-β and IL-13." (PMID 28004808, 2016). "This indicates a shift towards an alternatively activated phenotype, which is consistent with the neuroprotective effects of IL-13 previously documented in CNS trauma models, where the benefits are largely mediated through microglia and macrophages rather than direct neuronal action." (PMID 40822305, 2025). "Furthermore, we show that elevation of IL-13 is a common phenomenon that takes place in rodents as well as human brains, and that in the condition of brain injury, IL-13 has fundamentally beneficial effects in protecting neuronal survival." (PMID 36639371, 2023). "A study suggested that IL-13 could activate the JAK1/STAT1 pathway to prevent neuronal death and restore brain functions after traumatic brain injury." (PMID 35757105, 2022).
ischemia (7 papers, 2014 to 2024). A hypoperfusion of the BLOOD through an organ or tissue caused by a PATHOLOGIC CONSTRICTION or obstruction of its BLOOD VESSELS, or an absence of BLOOD CIRCULATION. "IL-13 has been reported to enhance microglial/macrophage anti-inflammatory responses and reduce brain cell death due to ischemia." (PMID 38397833, 2024). "Removal of IL-4 and IL-13 during renal ischemia-reperfusion impedes recovery from ischemia-reperfusion injury, and correlates with a rise in M1 phenotype and a decline in M2 phenotype." (PMID 38879568, 2024). "It was demonstrated that the sustained or increased expression of endogenous anti-inflammatory cytokines (IL-4 and IL-13) contributed to neuronal survival from ischemia-reperfusion injury in the gerbil hippocampus after transient forebrain ischemia." (PMID 34679060, 2021). "Taken together, delivery of IL-13 enhances microglial/macrophage anti-inflammatory responses in vivo and in vitro, decreases ischemia-induced brain cell death, and improves sensory and motor functions in the pMCAo mouse model of cerebral ischemia." (PMID 31372938, 2019). "Furthermore, IL-13 treatment ameliorated gait disturbances at day 7 and 14 and sensorimotor deficits at day 14 post-ischemia, as analyzed by the CatWalk gait analysis system and adhesive removal test, respectively." (PMID 31372938, 2019). "Because IL-13 can effectively trigger a shift from M1 to M2a state and attenuate the production of inflammatory mediators, we aimed to elucidate whether IL-13 is able to reduce neuroinflammation and thus protect from ischemia-induced brain damage." (PMID 31372938, 2019). "Here, we present for the first time that transplantation of IL13-expressing MSCs at 48 h after ischemia shifts major players of the immune reaction, namely microglia and macrophages, towards an anti-inflammatory, neuroprotective phenotype at 14 days after ischemia." (PMID 29866203, 2018). "Astrogliosis was not substantially affected by IL-13 treatment, as we observed similar levels of GFAP immunoreactivity following ischemia in vehicle and IL-13-treated mice." (PMID 31372938, 2019).
keratoconus (7 papers, 2011 to 2025). A degenerative, structural disorder of the eye, characterized by a cone-shaped protrusion of the cornea. "Interesting reports by Fodor M suggest that the level of NGF, in combination with IL-13, can predict corneal keratoconus progression with 100% specificity and 80% sensitivity." (PMID 38203537, 2023). "Levels of IL-6 and IL-17 were increased, while IL-12, CCL5, and IL-13 were decreased in keratoconus tear fluids compared with control." (PMID 27403376, 2016). "Low levels of IL-13 have been detected in severe keratoconus, as well as high levels in Graves' orbitopathy." (PMID 25371908, 2014). "The decreases in IL-12, TNF-α and CCL5 were statistically significant, while the IL-13 decrease was statistically significant in the severe keratoconus group only." (PMID 21298010, 2011). "The multiplex data implicate reductions in TH1 (IL-12, TNF-α, IFN-γ), and possibly TH2 cytokines (IL-4 and IL-13) in keratoconus." (PMID 21298010, 2011). "Both IL-4 and IL-13 cytokines were also reduced in keratoconus, and the decrease in IL-4, as measured by conventional ELISA, was statistically significant." (PMID 21298010, 2011). "Their findings indicate that the tear level of IL-13, in conjunction with NGF, can reliably predict the advancement of keratoconus, boasting a specificity of 100% and a sensitivity of 80%." (PMID 38256126, 2024). "Thus, decreases in IL-4 and IL-13 suggest that TH2 responses may be dampened in keratoconus." (PMID 21298010, 2011). "Interleukin (IL)-1β, IL-4, IL-6, IL-10, IL-12, IL-13, IL-17, interferon (IFN)-γ, chemokine C-C motif ligand 5 (CCL5) and tumor necrosis factor (TNF)-α were tested in tear samples and sera of keratoconus and control individuals by multiplex immuno-bead assays." (PMID 21298010, 2011).